MSR1 (macrophage scavenger receptor 1)
Diseases named in the same sentence as MSR1 in open-access papers (continued):
Sharing a sentence is not in itself a finding about the gene and the disease.
cancer (88 papers, 2007 to 2025). A tumor composed of atypical neoplastic, often pleomorphic cells that invade other tissues. "MSR1/CD204 can be expressed by primary AML cells as well as cancer- and AML-associated macrophages of the M2 phenotype." (PMID 40565207, 2025). "Beyond this role, MSR1 has been implicated in different human pathologies and very recently in cancer progression." (PMID 38612803, 2024). "CD204/MSR1 is a critical marker of TAMs and has been associated with cancer progression and poor prognosis." (PMID 38370385, 2024). "The expression of MSR1 has been linked to significantly poor prognoses and the increased severity of multiple forms of cancer." (PMID 38612803, 2024). "In this article, we evaluated the expression of MSR1 in cancer, observing an association with the presence of macrophages, DCs and neutrophils, in addition to a clear prediction of the response to anti-PD (L) 1 and CTLA4 inhibitors." (PMID 38612803, 2024). "A high frequency of M2‐polarized TAMs characterized by the expression of MSR1 is associated with poor prognosis in various cancers." (PMID 35142109, 2022). "In our study, we found that MSR1 + cell count was significantly associated with cancers in the repeat biopsy." (PMID 32860339, 2020). "However, there are an abundance of studies that show that MSR1 is an essential marker for TAMs and is associated with cancer progression and poor prognosis." (PMID 36325338, 2022). "In our study, after screening a group of biomarkers which may have potential field effects, we found that the immunoreactivity of p‐STAT3, Mcm2 + and/or MSR1 were associated with cancer and HGPCa at repeat biopsy." (PMID 32860339, 2020). "Additionally, MSR1 induces M2 macrophage polarization through the regulation of proline and arginine metabolism, and copy number variations (CNVs) in MSR1 may influence the risk of developing several types of cancer." (PMID 39776914, 2024). "An assessment of the MSR1 copy number in different cell lines would be helpful to verify its up-regulation in cancer." (PMID 39194722, 2024). "The upregulation of Msr1 (CD204) profoundly contributes to lipid accumulation in DCs in the cancer context." (PMID 37261073, 2023). "In this study, we evaluated the prognostic value of MSR1 in pan‐cancer and found that it has outstanding prognostic value in LGG patients, which prompted us to conduct further study." (PMID 35142109, 2022). "Further insights in the future will likely shed light on the molecular details of MSR1 functions, thus clarifying its clinical value for each inflammatory pathology and cancer." (PMID 36325338, 2022). "MSR1+ TAM populations have the potential to be used as an effective prognostic marker for various cancers." (PMID 36325338, 2022). "This gives one possible explanation as to how MSR1 becomes significantly upregulated in various cancers." (PMID 36325338, 2022). "In summary, MSR1 expression is frequently altered in cancer, but specifically in cells of the immune system." (PMID 36325338, 2022). "As ICPs inhibition is an effective treatment for many types of cancer, we explored the relationship between MSR1 and ICPs in LGG patients." (PMID 35142109, 2022). "The prognostic value of MSR1 in pan‐cancer was studied by using Cox regression analysis, the Kaplan–Meier method, and the log‐rank test." (PMID 35142109, 2022). "Unfortunately, the cancer cell derived molecules responsible for MSR1 upregulation are yet to be identified." (PMID 36325338, 2022). "Taken together, there is striking evidence that MSR1 is a valuable prognostic marker for the severity of multiple types of cancer." (PMID 36325338, 2022). "As MSR1 expression is already low in these cell types, it is unclear how MSR1 deletion contributes to the progression of cancer." (PMID 36325338, 2022). "We characterized five human patient samples with different types of cancers for the presence of MSR1." (PMID 31028084, 2019).
cancer (continued). "This coincided with increased activation of JNK pro‐inflammatory signalling pathway, suggesting that the MSR1‐JNK signalling pathway is activated in the progression of cancer." (PMID 31028084, 2019). "Adding further complexity to the effects of MSR1 in cancer, upregulation of the receptor is not always associated with poor prognosis." (PMID 36325338, 2022). "Whilst the relationship between MSR1 and cancer has mainly been represented as a correlation between increased expression and poor prognosis, there is also evidence that indicates isoform driven effects in cancer." (PMID 36325338, 2022). "As the collagen-like domain is the site for ligand binding, this may indicate that cancer derived ligands work via MSR1 to help drive the formation of the metastatic form of the disease." (PMID 36325338, 2022). "Finally p‐STAT3, Mcm2, and MSR1 were used to construct the model for predicting cancers in the repeat biopsy cohort." (PMID 32860339, 2020). "In addition, hypermutation of MSR1 elements within cancer cells might further promote gene dysregulation." (PMID 26781568, 2016). "It was previously reported that cancer-derived MUC2 could initiate intracellular signaling by binding to the macrophage scavenger receptor (MSR1) on the surface of infiltrating monocytes/macrophages, promoting the upregulation of intracellular COX-2 gene expression in these cells." (PMID 24324582, 2013). "Initial steps include analytical validation of a serum assay panel (p-cresol, S1P, 7-HOCA, DLST, MSR1, PGAM2, and ATG5) as well as known hallmarks of cancer proteins with standardized pre-analytics and central IDH and MGMT testing." (PMID 41294712, 2025). "The activity of c-Jun and STAT2 in the regulation of MSR1 is interesting as the JAK/STAT and JNK/SAPK pathways are also involved in leptin-induced chemotaxis of monocytes, macrophages, and cancer cells." (PMID 36325338, 2022). "However, MSR1 was not catalogued as a cancer driver by the IntOGen-mutations platform." (PMID 36325338, 2022). "e is natural logarithm and when predicting cancers, P = p‐STAT3 × 0.009138 + MSR1 × −0.005494 + Mcm2 × 0.133981 + (−0.654652)." (PMID 32860339, 2020). "Only one differentially expressed repeated sequence, a minisatellite repeat, MSR1, was up-regulated in all cancer samples but not in ESCs." (PMID 39194722, 2024). "Conversely, tandemly repeated sequences (MSR1, CER, ALR) showed up-regulation in cancer contexts." (PMID 39194722, 2024). "MSR1 is emerging as an important TAM marker, with recent studies linking high expression levels of the receptor to a significantly poor prognosis and increased severity of multiple forms of cancer." (PMID 36325338, 2022). "The pan-cancer analysis of single myeloid cells across 15 human cancer types unveiled significant findings, indicating that AMs express genes such as FABP4, MARCO, MRC1( also known as CD206), MSR1 and PPAR-γ, which are involved in self-replenishment through the secretion of (TGF-β." (PMID 38229178, 2024).
infection (15 papers, 2009 to 2025). The state of being infected such as from the introduction of a foreign agent such as serum, vaccine, antigenic substance or organism. "Mice with genetic deficiency of the homolog of MSR1 demonstrate increased susceptibility to infection with herpes simplex virus, while MSR1 is required for induction of TLR3-mediated signaling in monocytes exposed to human cytomegalovirus." (PMID 23717201, 2013). "It is very interesting to explore the potential roles between the expression of MSR1 and the pathogen infection in IPF patients." (PMID 33604393, 2021). "We report that MSR1 activates autophagy to restrict infection of Chikungunya virus (CHIKV), an arthritogenic alphavirus that causes acute and chronic crippling arthralgia." (PMID 33033362, 2020). "Indeed, the viremia in Msr1−/− mice at days 2 through 5 after infection was significantly higher than that in WT mice." (PMID 33033362, 2020). "Moreover, MSR1 expression was dramatically upregulated in mice at the very early stage of CHIKV infection (12 h after infection), way before the peak of viremia (48 h) and ISG expression (96 h)." (PMID 33033362, 2020). "We also observed a suppressed expression of MSR-1, a scavenger receptor of oxidized-LDL (ox-LDL), in LD-R infected murine liver, suggesting LD-R-infection limits the uptake of ox-LDL, reducing inflammatory responses." (PMID 40424189, 2025). "Confocal images and western blot analysis confirmed a significant lower expression of MSR-1 in LD-R-infected-KCs as compared to LD-S-infected-KCs, thus explaining reduced staining for ox-LDL in response to LD-R-infection." (PMID 40424189, 2025). "Indeed, MSR1 localizes to LC3-postive membrane structures after infection and non-autophagosomal membrane-associated LC3 could restrict RNA virus replication." (PMID 33033362, 2020). "Intriguingly, Msr1 mRNA expression was upregulated rapidly by CHIKV in blood cells of wild-type (WT) mice, with a peak at 12–24 h post infection (p.i.)." (PMID 33033362, 2020). "As MSR1 was predicted to be non-pathogenic based on in silico analysis, future research could verify this through experimental approaches such as in vitro cytotoxicity assays, in vivo infection models, or evaluation of virulence-associated phenotypes to confirm its safety for potential applications." (PMID 41385521, 2025). "Though the expression of Msr1 and Marco was induced with infection, no significant changes were observed in tlr2-null macrophages or in the absence of Jmjd3, H3K27me3 demethylase." (PMID 27532872, 2016). "We did not observe a consistent decrease of MSR1 protein by flow cytometry in PR/8-infected AM, which might explain why the infection did not impair the bacterial uptake (data not shown)." (PMID 22396727, 2012). "Consistent with the results from microarray experiments, PR/8 infection significantly decreased the mRNA levels of CLEC7A (Dectin 1), macrophage scavenger receptor 1 (MSR1), CD36, and the mannose receptor C type 1 (MRC1) but did not change the expression of MRC2." (PMID 22396727, 2012).
neurodegenerative disease (3 papers, 2019 to 2022). A disorder of the central nervous system characterized by gradual and progressive loss of neural tissue and neurologic function. "In light of the reported role of MSR1 in neurodegenerative diseases, we further focused on this scavenger receptor." (PMID 30692527, 2019). "Drugs MSR1 and MSR2 were also tested in several C. elegans models of human neurodegenerative diseases." (PMID 35890250, 2022).
cardiovascular disease (2 papers, 2018 to 2019). "Macrophage scavenger receptor 1 (MSR1) and macrophage receptor with collagenous structure (MARCO) are scavenger receptors that have been implicated in lipoprotein metabolism and cardiovascular disease." (PMID 30485705, 2018). "This warrants investigation of the role of MSR1 in glucose metabolism versus cardiovascular disease." (PMID 30485705, 2018).
inflammation (2 papers, 2021 to 2022). Aberrant reaction of the microcirculation characterized by movement of fluid and leukocytes from the blood into extravascular tissues. "Blocking macrophage scavenger receptor 1 (MSR1) in vitro reduced saturated fatty acid-induced inflammatory gene expression in primary MFs and in vivo administration of an anti-MSR1 antibody ameliorated liver inflammation in a NAFLD mouse model." (PMID 34831182, 2021). "More importantly, hypoxia increases the expression of MSR1 and inflammatory cytokines in adipose tissue of morbid-obese patients, and HIF-1α silence suppresses MSR1 expression and adipose inflammation." (PMID 36591228, 2022).
liver (1 paper, 2024). "Interestingly, correlation analysis in PWS significantly associated Ribokinase (RBKS), KYNU, Macrophage Scavenger Receptor 1 (MSR1), and SMPD1 with metabolic and liver dysfunction markers, such as transaminases, triglycerides, glycemia, and glycated hemoglobin." (PMID 39407757, 2024).
MSR1 also shares sentences with these, for which no sentence is quoted: lymph node metastasis (13 papers); lymphoma (9); lung adenocarcinoma (8); osteosarcoma (6); esophageal squamous cell carcinoma (5); esophageal cancer (4); idiopathic pulmonary fibrosis (4); systemic sclerosis (4); cervical cancer (3); clear cell renal cell carcinoma (3); histiocytic sarcoma (3); non-small cell lung carcinoma (3); sarcoma (3); adenocarcinoma (2); Bacterial Infections (2); breast tumor (2); cutaneous melanoma (2); gastric tumor (2); histiocytoma (2); metastatic tumor (2); neuropathies (2); osteoporosis (2); pancreatic adenocarcinoma (2); parasitic infections (2); prostate adenocarcinoma (2); renal fibrosis (2); respiratory disease (2); soft tissue sarcoma (2); abdominal aortic aneurysm (1); acute respiratory distress syndrome (1).
A further 75 diseases each share a sentence with MSR1 in 1 paper.